PARP1 (poly(ADP-ribose) polymerase 1)
Diseases named in the same sentence as PARP1 in open-access papers (continued):
Sharing a sentence is not in itself a finding about the gene and the disease.
cancer (continued). "Although parthanatos is characterized by PARP‐1 overactivation, clinically approved PARP‐1 inhibitors for the treatment of cancer have not been repurposed for other disorders." (PMID 36125899, 2022). "Rucaparib (RCP) is a potent selective inhibitor of both PARP-1 and PARP-2, which induces synthetic lethality in cancer cells that are not able to repair DNA damage by the HRR pathway." (PMID 35236893, 2022). "Since PARGi response is most robust when in concert with PARP1 activation and PAR formation, it is therefore not surprising that PARGi/IR co-treatment promotes cancer cell death." (PMID 34806016, 2021). "In these cancers, the use of PARP inhibitors has become the mainstay treatment, as the inhibition of PARP1 is not compensated by a functional HR response." (PMID 35008191, 2021). "In MKN28 and other sensitive cancer cell lines (AGS and SNU601), but not in SNU719 cells, BI-2536 elicited PARP1 cleavage, JNK phosphorylation and caspase-3 cleavage, all of which are indicative of apoptosis induction." (PMID 32486290, 2020). "Whereas PARP1-inhibitors also blocks BER, targeting the BER pathway as such has not been validated as an anti-cancer target." (PMID 33211885, 2020). "And similar to PARP1 knockdown, veliparib did not synergize with ATL to inhibit the clonogenic survival of the PC-3, SW480 and A549 cancer cells, despite that both veliparib and olaparib efficiently suppressed PAR accumulation." (PMID 32029902, 2020). "Can olaparib (an inhibitor of PARP-1 and PARP-2, approved after clinical trial) in combination with 12C ion radiotherapy be a better modality to control cancer metastasis irrespective of its efficiency in repair pathways?" (PMID 31438892, 2019). "Cancer cells lacking functional BRCA1 or BRCA2, critical players in HRR, were found to be particularly sensitive to PARP1 inhibition." (PMID 29684820, 2018). "The expression of PARP1, BRCA1 and BRCA2 was not correlated with cancer patients' age, TNM Stage, and pathological pattern of cancer." (PMID 25865228, 2015). "The effectiveness of PARPi in anti-cancer therapy requires that its target PARP-1 is available for inhibition; because in PARPi-treated cells, PARP-1 will still bind to DNA strand breaks but will not be activated to form PAR or facilitate DNA repair events." (PMID 23450678, 2013). "Each has been previously individually evaluated in chemotherapy, but the effects of combination PARP-1 and PARG inhibition in cancer cells are not known." (PMID 23254695, 2013). "While the expression level of PARP1 was universally higher in B-ALL samples, we found the levels of key mitotic and cell cycle regulators were not elevated in Dx and R samples relative to non-cancer BM controls." (PMID 37989729, 2023). "Treatment with NOT significantly attenuated cancer stem cells (CSCs)-like phenotypes, namely colony and tumorsphere formation, with the concomitant downregulation of stemness markers OCT4, SOX2, CD133, and upregulated PARP-1 cleavage, dose-dependently." (PMID 37299411, 2023). "However, in contrast to other cancers, we did not observe MYC-mediated transcriptional activation of DDR genes such as CHK1, PARP1, PARP2, and BRCA144–46." (PMID 31266951, 2019). "However, it is not known if the targeting of both PARP-1 and PARG in cancer cells can lead to a synergistic increase in cancer cell death." (PMID 23254695, 2013). "Thus, the results indicate that inhibiting both PARP-1 and PARG, which both are chemotherapeutic targets that increase cancer cell death, does not lead to synergistic cell death in HeLa cells." (PMID 23254695, 2013). "In this study, we explored associations between genotypes of base-excision repair genes (PARP1 Val762Ala, APEX1 Asp148Glu, and XRCC1 Arg399Gln) and in vitro BPDE-induced DNA adducts in cultured peripheral blood lymphocytes in 706 cancer-free non-Hispanic white subjects." (PMID 22792228, 2012).
cancer (continued). "It was shown in both cancer cells and tumours that a lack of oestrogen and progesterone receptors correlated with decreased levels of proteins found in the DNA-PK dependent NHEJ pathway and increased levels of proteins in the backup pathway, such as PARP1." (PMID 24970153, 2012). "PARP-1 is overexpressed in several human cancers, including CRC, in which the expression of PARP-1 seems not to be homogenous in tumour cells, but it is highly expressed in CSCs compared with non-CSCs, indicating that PARP-1 could regulate CSC programming, as previously reported." (PMID 36902215, 2023). "Remarkably, while a time dependent increase in uptake was observed in almost all cancer cell lines irrespective of pre-treatments (except SKBR3), the mammary epithelial cell line MCF10A showed time dependent decrease despite of detected high cellular PARP1 expression." (PMID 35008392, 2022). "Thus, combining PARP1 and RAD52 inhibitors to treat BRCA1 or BRCA2 mutant cancers might provide little or no therapeutic gain, and might increase normal tissue toxicity." (PMID 29145865, 2017). "Although these outcomes can be separated by PARP-1 activity (protein binding versus enzymatic function), pharmacologic inhibition of PARP affect both actions, indicating manipulation of chromatin accessibility through PARP-1 is not currently an option for cancer therapy." (PMID 24350055, 2013). "Therefore, although we have shown that inhibition of both PARP-1 and PARG does not increase cell death in HeLa cells, we have further shown that PARG inhibition may provide an innovative strategy to treat specific types of cancer." (PMID 23254695, 2013).
tumor (989 papers, 1986 to 2026). "For example, targeting the BER pathway in combination with PARP1, a factor in the HR pathway, can cause synthetic lethality to inhibit tumour cell growth." (PMID 40916080, 2025). "UNI66, another inhibitor of BRD4, suppresses HR by inhibiting BRD4-mediated transcription of CtBP-interacting protein (CtIP) and RAD51, thereby inducing synthetic lethality in PARP1-deficient cells and enhancing tumor sensitivity to PARPis." (PMID 41190241, 2025). "Whereas, in the poly-(ADP-ribose)-polymerase-1 (PARP1), a gene encodes an enzyme that modifies several proteins involved in the regulation of several important cellular processes, such as tumor proliferation and transformation." (PMID 39058128, 2024). "P97 complex inhibitors prolong PARP1 trapping and enhance PARPi-related cytotoxicity in HR-deficient tumor cells." (PMID 37588193, 2024). "They identified a PARP-1 mutation (R591C) commonly observed in PARPi-resistant patient tumor samples, which was associated with diminished trapping of PARP-1 on DNA, resulting in PARPi resistance." (PMID 38236558, 2024). "Since BRCA1/2-mutant tumor cells are deficient in HR-mediated DNA repair, they are especially reliant on PARP1/2 for their survival." (PMID 38956205, 2024). "Targeting PARP1 with inhibitors can expose tumor cells to DNA-damaging agents, making them more susceptible to chemotherapy and radiation." (PMID 39456202, 2024). "Strikingly, the loss or diminished expression of PARP1 in tumor cells causes PARPi resistance, demonstrating the key role of PARP1 trapping in subsequent DDR and PARPi‐mediated cytotoxicity." (PMID 38973255, 2024). "We performed TWAS of clinical outcome and lab-derived phenotypes from the central regulators of ferroptosis, cuproptosis, and parthanatos and identified strong associations between PARP1 and neoplasms and platelet traits." (PMID 38589365, 2024). "Overall, increasing the tumor mutational burden by PARP1 degradation and mitochondrial deregulation makes CML suitable for immunotherapy." (PMID 38704604, 2024). "Elevated PARP-1 activity is implicated in several mechanisms that contribute to tumor cell resistance to therapy." (PMID 39682189, 2024). "HRR-deficient neoplasms are extremely susceptive to PARP1 inhibitors based on the synthetic lethality theory." (PMID 38907095, 2024). "PARP1 inhibitors in combination with other drugs such as EGFR inhibitors and CDK12 inhibitors can increase the sensitivity of tumor cells to PARP1 inhibitors by inducing HR-deficient." (PMID 39679370, 2024). "Functioning of all alternative pathways rely on PARP1 and PARP2 enzymes and inhibition of PARP1/2 enzymes in BRCA1/2-deficient tumor cells results in cell death." (PMID 37945748, 2023). "In another investigation, a reduction in tumor burden was observed in mice that were genetically deficient for PARP-1 and PARP-2 expression and activity through increased oxidative stress." (PMID 36768904, 2023). "PARP-1 is overexpressed in the tumour tissue compared to healthy mucosa, being associated with the differentiation grade." (PMID 36902215, 2023). "It was demonstrated that PARG depletion restored PARP1 signalling and led to PARPi resistance in HR-deficient tumours." (PMID 37190285, 2023). "Elevated PARP-1 expression has been found in several tumours, being associated with stemness and tumorigenesis." (PMID 36902215, 2023).
tumor (continued). "As far as we know, this is the first study exploring the effectiveness of a 77Br linked PARP-1 inhibitor in in vivo xenograft tumor models." (PMID 36834491, 2023). "Accordingly, RT associated with the inhibition of both c-Met and PARP-1 resulted in a synergistic effect not only on tumor growth inhibition but also on tumor regrowth control in all animals following the stop of the treatment." (PMID 37215708, 2023). "Described mutations in PARP1, such as p.R591C in PARPi-resistant tumour samples, were linked to a diminished PARP1 trapping activity on DNA." (PMID 37430137, 2023). "Similar to other described resistance mechanisms to PARPi, the incidence of acquired or existing PARP1 mutations in tumours remains poorly defined." (PMID 37430137, 2023). "PARP-1 mutation R591C, recently identified in the tumour of a PARPi-resistant patient, was found to prevent PARP-1 trapping, providing the first clinical evidence linking PARPi resistance with loss of PARP-trapping ability." (PMID 37609662, 2023). "PARP inhibitors mediate selective cytotoxicity as they introduce even more DSBs in tumour cells with deficient HRR by inhibiting PARP1, responsible for single-strand break repair." (PMID 37568604, 2023). "Single PARP2-deficiency was shown to inhibit tumour progression while dual PARP1/PARP2-deficiency promotes tumour growth in T cells." (PMID 37667522, 2023). "In the example of BRCA mutations, these tumour cells harbour unrepaired SSBs, and, in this scenario, PARP-1 activation is fundamental to rescuing DNA damage and cell death." (PMID 35158955, 2022). "Currently, inhibiting RAD52 and/or PARP1 in the tumor cells that are deficient in the canonical repair pathways has been the potential target for inducing the effect of synthetic lethality." (PMID 35741863, 2022). "Previous studies also demonstrated that BRCA1 mutation and PARP1 activity also influence tumor metabolism." (PMID 35211121, 2022). "PARP1 encodes a chromatin-associated enzyme involved in the regulation of differentiation, proliferation, tumor transformation, and DNA damage." (PMID 35379887, 2022). "Another mechanism of PARPi resistance in BRCA1/2-deficient tumor cells is due to the downregulation of PARP1 expression, thereby resulting in PARylation-independent cell proliferation and/or the inefficiency of PARP1 trapping by PARPi." (PMID 36497275, 2022). "According to the theory of combined lethality, radiotherapy and chemotherapy cause DNA damage in tumor cells, combined with the inhibitory effect of PARP-1 on DNA repair, resulting in a more potent cytotoxic effect on tumor cells." (PMID 36092717, 2022). "PARP1/2 inhibitors yielded encouraging results in combination with immune checkpoint inhibitors by promoting neoantigen release, increasing tumor mutational burden, and enhancing PD-L1 expression." (PMID 35910366, 2022). "BRCA1- or BRCA2- deficient tumor cells were shown to be highly sensitive to pharmaceutical inhibition of poly (ADP-ribose) polymerase 1 (PARP1), a protein involved in the repair of single-strand DNA breaks (SSBs)." (PMID 36186482, 2022). "PARPis are specifically lethal to BRCA1/2‐deficient tumours because PARP1/2 enzymes, the targets of PARPi, bind to DNA ends." (PMID 35107878, 2022). "WB analyses of tumor tissues revealed that Fdcyd treatment significantly induced γH2AX levels, as well as PARP1 cleavage in PBRM1-deficient 786-O tumors." (PMID 35719970, 2022). "General enhancement of PARP-1 activity is associated with the development of tumor, cardiovascular and neurodegenerative diseases, and pharmacological inhibition of PARP-1 is a promising strategy for their therapy." (PMID 34768872, 2021).
tumor (continued). "HR is required for DSB repair, and HR-deficiency is a typical pathological feature of the BRCA1/2-mutated tumor and enables enhanced response to PARP1 inhibition due to synthetic lethality." (PMID 34631532, 2021). "PARP1 inhibitors cause replication stress by inhibiting PARP1-dependent repair of single-strand damage and from PARP1-trapping on damaged DNA, accounting for the synthetic lethality of PARP1 inhibitors in HR-deficient tumor cells." (PMID 34337349, 2021). "PARP-1 impedes with cell differentiation thus enhancing tumor malignancy, and moderate activation of PARP-1 caused by the accumulation of DNA damage during intensive cell division increases DNA repair efficiency and cell viability." (PMID 34768872, 2021). "We analyzed the relationship between PARP1 alterations and tumor mutation burden (TMB) level, immune cell infiltrations, along with microsatellite instability (MSI) event." (PMID 34531868, 2021). "Cells deficient in RAD51-mediated HDR through the inactivation of tumor suppressor genes like BRCA1 or BRCA2 exhibit hypersensitivity to poly-ADP ribose polymerase 1 (PARP1) inhibitors." (PMID 33662256, 2021). "Meanwhile, The TGFβ1 level in tumor stroma was positively associated with both PARP1 and cleaved-PARP1 in tumor by immunohistochemical analyses (P ≤ 0.001, R = 0.430; P = 0.064, R = 0.206)." (PMID 34095135, 2021). "In 2005, two crucial papers demonstrated the hypersensitivity of BRCA1/2 deficient tumor cells to PARP1 inhibitors (PARPi)." (PMID 33498235, 2021). "A third mechanism is through the mutation of PARP1 in tumor cells preventing trapping and cytotoxicity to these cells." (PMID 34884434, 2021). "PARP-1 plays an important role in the functioning of the tumor microenvironment, participating in angiogenesis as well as in the formation of a tumor-associated stroma." (PMID 34768872, 2021). "The demonstrated associations with recognized prognostic factors—loss of chromosome 3, tumor size, and histopathological grade—indicates that high PARP-1 expression can be considered an unfavorable prognostic factor in UM." (PMID 33572586, 2021). "Our study revealed upregulation of PARP1 expression in at least some recurrent oral tumor cells, as one of the underlying mechanisms of treatment resistance and tumor recurrence." (PMID 35071239, 2021). "Perhaps the best known example of such phenomenon involves mutations and/or low expression of BRCA1/2, whereby HR deficiency sensitizes tumor cells to inhibit PARP1, a critical mediator of the corresponding DNA single-strand break repair pathway." (PMID 33138032, 2020). "Previous studies have shown that homologous recombination-deficient tumor cells resulting from BRCA1 or BRCA2 gene mutations are hypersensitive to the inhibitory effect of poly-ADP ribose polymerase-1 (PARP-1)." (PMID 32509471, 2020). "Supportive of compensatory roles, co-deletion of PARP1 and PARP2 results in embryonic lethality, however, PARP1−/− mice exhibit increased spontaneous tumor incidence suggesting PARP2 cannot fully compensate for PARP1 loss." (PMID 33005627, 2020). "Accordingly, T cell lymphopenia in dual PARP-1/PARP-2-deficient mice can affect the recruitment of lymphocytes to the tumor microenvironment." (PMID 32046278, 2020). "The blockade of PARP1 through the use of PARP inhibitors or alkylating agents causes accumulation of DNA damages in DDR-defective tumor cells, resulting in a synthetic lethality." (PMID 32963528, 2020). "Treatment of EL4 (murine) or BT549 (human) tumor cells with InhiTinib caused the processing of PARP-1 and induction of γH2AX." (PMID 32231565, 2020). "PARP-1 inhibition in BRCA-defective tumours is expected to cause unrepaired double-stranded breaks in DNA." (PMID 31080552, 2019). "In the present study, we have identified the chromatin‐binding protein HMGA2 as a new endogenous modulator of PARP1 activity causing accelerated and enhanced PARylation upon DNA damage in human tumor cells." (PMID 30289618, 2019).